ALB (albumin)
Diseases named in the same sentence as ALB in open-access papers (continued):
Sharing a sentence is not in itself a finding about the gene and the disease.
Stroke (continued). "In our study, the non-ADPKD cohort had a higher prevalence of CHF, atherosclerotic heart disease, peripheral vascular disease, cerebrovascular accident, and had a higher BMI and lower serum albumin, all suggestive of a less healthy patient population compared to the ADPKD cohort." (PMID 24571546, 2014). "Additionally, compared to NHANES, mean concentrations of albumin, as well as hemoglobin, were lower in stroke." (PMID 25530905, 2014). "The prevalence of low albumin was higher in AA versus C stroke participants." (PMID 25530905, 2014). "Univariate binary logistic regression analysis revealed that a very advanced age, basin group, serum albumin levels, serum creatinine levels, non-anuria, and the complications of stroke and CAD were associated with 2-year mortality." (PMID 24058552, 2013). "Serum albumin is a negative acute phase protein and concentration falls between day 1 and day 7 after stroke onset, which could possibly explain the finding of marginally low serum albumin in our series." (PMID 23565300, 2013). "Relationship between serum albumin and stroke outcome was determined." (PMID 23565300, 2013). "Various mechanisms have been proposed to explain the effect of serum albumin on stroke outcome." (PMID 23565300, 2013). "In this study, we could demonstrate that after adjustment for very advanced age, gender, and log hs-CRP, serum albumin levels, living in Taipei Basin, and the complications of stroke and CAD, the 2-year mortality in elderly HD patients could be predicted." (PMID 24058552, 2013). "Albumin also antagonize thrombosis, stagnation and leukocyte adhesion within the post capillary microcirculation in early reperfusion phase of stroke thus offering neuro protection in stroke patients." (PMID 23565300, 2013). "This is similar to finding of relatively low serum albumin in our stroke patient." (PMID 23565300, 2013). "However, we have illustrated that reduced serum albumin is an accompaniment of ischaemic stroke in our environment, correlates with stroke severity and independently predicts adverse outcome including fatality and functional impairment." (PMID 23565300, 2013). "Predictors of mortality included: age; male gender; social deprivation; history of cancer, renal disease, stroke, ischaemic heart disease or respiratory disease; statin use; and LFTs (albumin, transaminase, alkaline phosphatase, bilirubin, and gamma-glutamyltransferase)." (PMID 23272082, 2012). "These predictors include age, stroke, cancer, albumin and ferritin." (PMID 21569355, 2011). "While LDH and ALB have been individually associated with prognosis in stroke and critical illness, ICH-specific evidence on the combined index is limited; however, LAR has shown prognostic associations in related acute conditions (e.g., stroke-associated pneumonia; severe infection/ICU cohorts)." (PMID 41487425, 2025). "BBB function may also be assessed in stroke patients using the cerebrospinal fluid (CSF)-to-plasma albumin ratio, as albumin represents a serum protein of large molecular weight which is prevented by the BBB from entering the brain under physiological conditions." (PMID 41295436, 2025). "The neutrophil-to-albumin ratio (NPAR) is a relatively novel composite biomarker of inflammation, which has been used for prognostication in cardiovascular diseases and may also be associated with stroke." (PMID 39935611, 2025). "Furthermore, researchers have exploratorily conducted studies on whether supplementing albumin can improve the prognosis of stroke patients." (PMID 40353064, 2025). "Finally, correlation of serum albumin with the severity and the outcome of stroke (mRS) was made." (PMID 40655892, 2024). "Consequently, inflammation could affect the prognosis of stroke patients not only directly but also indirectly through albumin and BMI." (PMID 38699426, 2024). "Finally, with respect to blood tests, low albumin significantly increased the incidence of stroke." (PMID 37848510, 2023).
Stroke (continued). "Also, this research may offer a preliminary, scientific, proof medical evaluation of whether variations in serum albumin levels impact stroke frequency." (PMID 37682189, 2023). "Since the protective role is so significant, high-dose albumin has been shown to be highly neuroprotective during strokes, and multicenter clinical trials have been carried out, but the neuroprotective function of albumin remains unknown and our data shed light on these possible mechanisms." (PMID 36077089, 2022). "Serum albumin, prealbumin, and transferrin levels were associated with ANS function, as measured by HRV, and their deficiency may be a predictive factor for the severity of ANS dysfunction in stroke patients." (PMID 36558479, 2022). "Similarly, in the model 2 adjusted for age, sex, hemodialysis, prior stroke, prior myocardial infarction and prior heart failure hospitalization, and model 3 adjusted for age, sex, and levels of hemoglobin, albumin, eGFR and C-reactive protein, both low LBMI and low BF% also predicted mortality." (PMID 34097103, 2021). "Moreover, patients with low albumin levels may also have co-morbid chronic illnesses or neurological conditions that can halt their recovery from stroke." (PMID 33959442, 2021). "Based on physiological characteristics of albumin, namely, antioxidant, anti-inflammatory, anticoagulant, and antiplatelet aggregation activity and regulation of microvascular permeability, albumin could be used to predict the pulmonary infection after stroke." (PMID 35095715, 2021). "Moreover, albumin could also reflect the nutritional status of the patients, which was related to the complications of stroke." (PMID 34604286, 2021). "ALB before stroke may be one of the predictors of stroke severity." (PMID 33505489, 2021). "In a recent, large cohort study, patients with type 2 diabetes who had levels of HbA1c, cholesterol, serum albumin and blood pressure all within target ranges, and who did not smoke, were at similar risk of myocardial infarction or stroke as age-, sex- and country-matched controls." (PMID 30486889, 2018). "Moreover, subsequent transcriptional responses to the injury was greater at 24 h compared to 12 h following the onset of stroke in the present study, suggesting that the effect of albumin on ECM remodeling might be delayed." (PMID 28794441, 2017). "Notably, plasma levels of neurogranin 72 h after stroke were weakly inversely related to the CSF/serum ratio of albumin (r = −0.330; P < 0.05) and, at 3 months after stroke onset, to the distance between the infarction and the ventricles (r = −0.688; P < 0.05)." (PMID 28854881, 2017). "Given that stroke involves BBB dysfunction and its extent may vary with infarct sizes, additional albumin administration for stroke patients may induce massive albumin exposure to broad brain regions, resulting in adverse events including intracerebral hemorrhage." (PMID 28794441, 2017). "Accordingly, we could not determine if the detected urine albumin reflected premorbid impaired renal status or renal change reactive to systemic inflammation associated with an index stroke event." (PMID 27213281, 2016). "Thus, coinciding with the MRI measurements, histological results of H&E and albumin stainings for BBB damage demonstrated that BMSC treatment of stroke in T2DM rats significantly reduced cerebral vascular leakage after stroke and substantially reduced hemorrhage compared to the control T2DM rats." (PMID 26900843, 2016). "The finalized predictive model incorporated five independent predictors, including stroke subtype, age, ADL assessment, serum albumin concentration, and white blood cell counts, which were subsequently operationalized into a clinically applicable nomogram." (PMID 40994717, 2025).
Stroke (continued). "For instance, studies have demonstrated a negative association between albumin and depression in stroke survivors, patients with chronic liver disease, and adolescents with systemic lupus erythematosus, hypothesizing that this association may be linked to oxidative stress and inflammatory responses." (PMID 40276074, 2025). "Tracheostomy status, aspiration on VFSS, cough frequency at 7.8 μM mCRT, albumin levels, and MMSE scores were identified as significant predictors of post-stroke pneumonia." (PMID 41346384, 2025). "A prior retrospective study indicated that NPAR is independently associated with stroke recurrence within 3 months following the first acute stroke, suggesting that NPAR might be a better predictor of acute ischemic stroke recurrence than albumin levels or neutrophil percentage alone." (PMID 39935611, 2025). "ROC analyses for these variables yielded the following AUCs: stroke subtype (AUC = 0.642), age (AUC = 0.756), ADL score (AUC = 0.839), albumin level (AUC = 0.754), and white blood cell count (AUC = 0.712)." (PMID 40994717, 2025). "The most regularized and reasonable model included five variables: stroke type, age, ADL score, albumin level, and white blood cell count, with the cross-validation error within one standard error of the minimum." (PMID 40994717, 2025). "Compared with controls, individuals with cancer displayed reduced ALB and taurine levels, exhibited a higher tendency to smoke, and had an increased incidence of prior coronary heart disease (CHD) and stroke events." (PMID 39744126, 2024). "The concentration of serum BNDF, NE, ET, and glutamate, and peripheral blood SOD, ALB, HB, and CAT suggest the function improvement of stroke patients." (PMID 39355076, 2024). "However, the mechanisms connecting serum albumin to daily mobility after stroke remain unclear." (PMID 39835151, 2024). "Data including demographic information, stroke severity, MASA, Oral Health Assessment Tool, body mass index, and serum albumin level were collected." (PMID 38558178, 2024). "After adjusting for confounding factors, multivariate analysis showed that for every 1 g/L increase in serum albumin levels, there was a 7% reduction in severe ADL impairment post-stroke." (PMID 39835151, 2024). "The observed disparities between the two groups were as follows: age (p < .001), outcomes (p < .001), stroke severity (p < .001), TOAST (p < .001), AF (p < .001), Hs‐CRP (p < .001), FBG (p = .024), Hba1c (p = .034), FIB (p < .001), and ALB (p < 0.001)." (PMID 38376013, 2024). "Compared with participants with both normal urine Albumin–Creatinine Ratio (UACR) and eGFR, those with UACR ≥ 30 mg/g and eGFR < 60 mL/min/1.73 m2 had increased risks of stroke." (PMID 38399507, 2024). "In summary, an L-shaped connection with an approximate inflection point of 38.0 g/L was found between blood albumin levels and significant ADL impairment in stroke patients." (PMID 39835151, 2024). "Stroke patients exhibited significantly elevated NLR values (p < 0.001) and reduced levels of platelets (p < 0.001), INR (p = 0.026), albumin (p = 0.025), total protein (p < 0.001), and cholesterol (p = 0.009)." (PMID 39125277, 2024). "Sensitivity analyses also reinforced the robustness of the observed relationship between serum albumin levels and severe ADL impairment after stroke." (PMID 39835151, 2024). "After adjusting for potential confounders, seven independent predictors of 30-day readmission were identified: age, stroke, intracerebral hemorrhage, ASA classification, blood glucose levels, serum albumin levels, and pneumonia." (PMID 38528491, 2024). "To summarize, our study found an L-shaped correlation between serum albumin levels and severe ADL impairment in stroke patients, with a critical threshold at around 38.0 g/L." (PMID 39835151, 2024). "The results revealed an L-shaped relationship between serum albumin levels and severely impaired ADL in stroke patients, with an inflection point at 38.0 g/L." (PMID 39835151, 2024).
Stroke (continued). "Our study findings indicated that participants with a TyG index > 8.96 had a greater likelihood of stroke than those with a TyG index < 8.11 (model 6, adjusted for cholesterol, LDL, Apo-B, creatinine, and urine albumin: adjusted odds ratio = 4.42)." (PMID 38954387, 2024). "After matching the data, we found that the drinking states of SBP, DBP, serum albumin, TG, TC, HDL-C, eGFR, antihypertensive agents and antiplatelet drug had significant differences between patients with stroke and non-stroke." (PMID 37113292, 2023). "The present study preliminarily deduced that serum BDNF, NE, ET and glutamate, and peripheral blood SOD, ALB, HB, and CAT can be used as indicators of functional recovery in stroke patients." (PMID 37731856, 2023). "This altered albumin permeability at the blood-CSF barrier was further analyzed by calculating the intracellular albumin intensity in CPECs, showing a 2–3-fold increase in the IL LVCP at 1–7 days post-stroke (P < 0.05)." (PMID 38107410, 2023). "Albumin levels have prognostic value in a variety of diseases, including COPD, stroke, atrial fibrillation, and heart failure." (PMID 36739380, 2023). "In elderly stroke patients, GNRI (in parallel with BMI and albumin) decreased during hospitalization, and these changes were related to age, AIS, severity of disease, and independence in ADL." (PMID 36771390, 2023). "We found a markedly decreased albumin level in the CXI of the μKO mice compared to the WT, indicating greater BBB preservation after stroke." (PMID 37777791, 2023). "They utilized NIHSS score, stroke volume, neutrophil, platelet, WBC, albumin, monocyte/HDL ratio, Ca+ and Glasgow coma scale as predictors of mortality." (PMID 36810474, 2023). "Additionally, GNRI may not hold a superiority over BMI in this context as serum albumin levels are associated with inflammatory responses and electrolyte abnormalities, common occurrences during the acute phase of stroke." (PMID 38115884, 2023). "A total of 10 variables such as age, race, BMI, direct HDL-cholesterol level, stroke history, DII, HbA1c, PHQ-9 score, sleep duration, and albumin level were selected to construct the model." (PMID 37179565, 2023). "L-4F treatment significantly decreased albumin density indicating improved BBB integrity and increased tight junction protein in the ischemic brain in both ABCA1−B/−B and ABCA1fl/fl T2DM-stroke mice measured by immunostaining (p < 0.05, n = 9/group)." (PMID 35572941, 2022). "Furthermore, there were evidence supported that HAE can be act as a strong prognostic factor for stroke in many observational studies, which supported the prognostic value of blood albumin for detecting stroke risk, irrespective of other specific or well-established risk factors." (PMID 35850629, 2022). "Nomogram 1, based on Hcy, hsCRP, and ALB levels, provided a more clinically realistic prognostic prediction for patients with PFO-related stroke." (PMID 35756923, 2022). "For haematologic and metabolic indicators, serum levels of CRP, TB, ALB and HCY in patients with stroke (both IS and HS group) were lower than those in the TIA group (all p < .05)." (PMID 35471128, 2022). "For the mediator models based on the categorical weight change variable, we identified age, smoking, alcohol use, walking, COPD, stroke, estrogen use, IGF-1, 25(OH)D, albumin, height, ln-SHBG, and ln-PTH as confounders." (PMID 34272641, 2022). "Storax significantly inhibited the fluorescent albumin intensity in the brain parenchyma and the number of caveolae in ECs, alongside attenuating the ultrastructural disruption of BBB at 6 h after stroke." (PMID 35873558, 2022). "Based on the results of the univariate analysis, the dominant factors correlated with stroke outcomes, including age, NIHSS, Baseline BI, Hb, and albumin, were incorporated in the multiple logistic regression analysis." (PMID 35544482, 2022).
Stroke (continued). "A decrease in serum albumin, creatinine, as well as ALT activity, are predictors of functional outcomes acute stroke and confirms the validity of the model." (PMID 34064017, 2021). "The core targets of PPI are TNF,IL-6,ALB,AKT1,VEGFA, and CREB1, which play a key role in the regulation of stroke by DZSM." (PMID 34754318, 2021). "In preclinical stroke models, BBB leakage is often evaluated at a single time point using albumin-bound Evans Blue dye or postmortem staining by immunoglobulin G, which are comparatively large molecules." (PMID 33305265, 2020). "In multivariable regression analysis, serum albumin level (adjusted odds ratio (AOR) = 0.123, 95% CI = (0.035–0.429)) and preexisting stroke (AOR = 11.447, 95% CI = (1.168–112.220)) significantly and independently predicted pneumonia detection by CT." (PMID 33260480, 2020). "The univariates affecting 2-year longevity were CHF, prior stroke, dialysis, ambulatory status, CLTI, BMI, total cholesterol, NLR, PLR, SII, CRP level, albumin, CONUT score, and GNRI." (PMID 33177036, 2020). "We suggest that BBB disruption remote from the photothrombotic stroke is only attenuated, but is severe enough to open the BBB for proteins of the size of albumin for hours before achieving the initial state again." (PMID 31430854, 2019). "Expression values for over 22,000 rat genes were scored and received a vote for each experiment in which the gene was dysregulated at 24 hours following insult (stroke, undercut, DOC, albumin, or TGFβ1)." (PMID 28794441, 2017). "Comorbid illness as a result of stroke and CAD, low serum albumin levels, and living in Taipei Basin were correlated with 2-year mortality." (PMID 24058552, 2013). "In a multivariate logistic regression admission stroke severity measured by NIHSS and serum albumin correlated with 30 days mortality in the presence of other variables (age, WBC, NIHSS, RBS and duration of formal education)." (PMID 23565300, 2013). "A univariate analysis including age, stroke comorbidity, APACHE II, septic shock, total calcium, albumin, 25(OH)D, 1,25(OH)2D, and PTH was performed for their clinical or statistical association with 30-day mortality." (PMID 23741318, 2013). "In stroke subjects, the Albumin in Acute Stroke (ALIAS) Trial showed a potential beneficial therapeutic effect for albumin, and the second part of the ALIAS trial has been started with more stringent exclusion criteria." (PMID 22507553, 2012). "This investigation effectively engineered an albumin‐specific covalently tagged near‐infrared‐II (NIR‐II) dye, serving as a chromophore, to construct fluorescent proteins in situ for evaluating BBB disruption during stroke." (PMID 39999308, 2025). "They found that albumin therapy did not significantly improve stroke outcomes and presented considerable risks, particularly pulmonary complications." (PMID 40332503, 2025). "There was a statistically significant difference in ALT, anion gap, AST, bicarbonate, calcium, glucose, INR, platelets, total bilirubin WBC, CPK, monocyte, EGFR, RDW, albumin, RAR, sex, calcium inhibitor, race, smoking, stroke, and AF between the survival and death groups (P < 0.05)." (PMID 40687564, 2025). "In this investigation, we employed restricted cubic splines (RCS) to rigorously analyze the relationships between the neutrophil-to-albumin ratio (NPAR) and various cardiovascular diseases, namely congestive heart failure (CHF), stroke, coronary heart disease (CHD), and angina pectoris." (PMID 40438231, 2025). "The serum creatinine-to-albumin ratio (sCAR), reflecting renal function and nutritional status, may offer improved mortality prediction for the intensive care unit (ICU)-admitted stroke patients." (PMID 41170336, 2025). "A RCT in 2020 demonstrates no rise in albumin after supplementation with whey protein in patients who have suffered a stroke." (PMID 38794724, 2024).